GDF15 (growth differentiation factor 15)
Diseases named in the same sentence as GDF15 in open-access papers (continued):
Sharing a sentence is not in itself a finding about the gene and the disease.
cardiac hypertrophy (33 papers, 2012 to 2025). "In a group of elderly individuals, GDF-15 was associated with lower ejection fraction, concentric LV remodelling and hypertrophy." (PMID 36001499, 2022). "While GDF-15 can show protection against cardiac hypertrophy, its increased expression is associated with the development and progression of atherosclerotic plaques." (PMID 26273671, 2015). "In addition, GDF-15 is implicated in cardiac hypertrophy which is described as an increased heart size and insufficient cardiac output." (PMID 35600479, 2022). "In the context of cardiac hypertrophy, GDF-15 works through both Smad-dependent signaling (like Smad2/3) and alternative, non-Smad routes such as MAPK and TAK1 pathways." (PMID 40283221, 2025). "Gdf15 is recognized as a SASP factor within the cardiovascular system, where its accumulation has been associated with the development of cardiac hypertrophy while Igfbp2 is another SASP protein associated with aging." (PMID 40607964, 2025). "GDF15 shows an anti-cardiac hypertrophy effect via the Smad2/3 pathway, whereas in cardiomyocytes cultured with GDF15, it exerted a pro-hypertrophic effect via the Smad1 pathway." (PMID 37093513, 2024). "GDF-15 plays a dual role in ventricular remodeling: it can promote myocardial fibrosis and collagen protein deposition while inhibiting myocardial hypertrophy." (PMID 38435138, 2024). "On the other hand, in experimental models, GDF-15 attenuates cardiac hypertrophy through the SMAD pathway and plays a protective role for heart and endothelial cells." (PMID 38409184, 2024). "GDF-15 regulates inflammatory pathways, apoptosis, cell repair, and growth, strongly linking it to cardiac hypertrophy and fibrosis." (PMID 38435138, 2024). "Another study showed that GDF-15 blocks norepinephrine-induced myocardial hypertrophy through a pathway involving inhibition of the epidermal growth factor receptor transactivation." (PMID 37189644, 2023). "For example, GDF-15 promotes cardiac hypertrophy by protecting cardiomyocytes from apoptotic stimuli, but in constrast GDF-15 also seems to reduce myocardial hypertrophy by inhibiting the transactivation of EGFR." (PMID 35600479, 2022). "In a pressure-overload murine model, GDF15 was also induced during cardiac hypertrophy, and its cardiac-specific overexpression protected the heart from hypertrophic responses." (PMID 34445593, 2021). "Transgenic mice that express GDF15 show normal phenotypes, but are resistant to cardiac hypertrophy induced by pressure overload." (PMID 29783655, 2018). "One of the recent studies shows that GDF-15 is an autocrine/paracrine factor that attenuates the cardiac hypertrophy in experimental models via SMAD and kinases (PI3 K and ERK) signaling pathways." (PMID 26273671, 2015). "GDF-15 was found to inhibit myocardial hypertrophy through a Smad2/3 pathway in a pressure-induced hypertrophy model." (PMID 26273671, 2015). "Conversely, GDF-15 gene targeted mice develops cardiac hypertrophy, suggesting that GDF-15 is a cardioprotective cytokine involved in the process of cardiac hypertrophy." (PMID 23071585, 2012). "Regarding cardiovascular effects, GDF-15 is thought to be involved in the inhibition of myocardial hypertrophy and may exert both atherogenic and antiatherogenic effects." (PMID 38668313, 2024). "GDF-15 was found to inhibit myocardial hypertrophy through a Smad2/3 pathway." (PMID 34445593, 2021). "GDF-15 was more likely to be elevated in children with PHIV, including those with LV diastolic dysfunction and hypertrophy." (PMID 36001499, 2022). "GDF15, a cardiac hypertrophy marker, is also reported to be a more sensitive and non-traditional biomarker for doxorubicin-induced cardiotoxicity." (PMID 34485421, 2021). "Because cardiac hypertrophy and interstitial fibrosis are common pathological features of HFpEF and HFmrEF, the prognostic value of GDF‐15 found in these patients is not entirely surprising." (PMID 32589369, 2020).
cardiac hypertrophy (continued). "Recently, accumulating evidence has shown that members of the TGF-β superfamily including growth differentiation factor-15 (GDF-15), myostatin, and activin A play a cardioprotective role in maintaining normal cardiac homeostasis and inhibiting myocardial hypertrophy." (PMID 29744364, 2018). "In ventricular hypertrophy or hypertensive heart disease, it was suggested that the thickness of the posterior wall, serum norepinephrine levels, and the left ventricular mass were positively correlated with elevated levels of GDF-15, which demonstrated the possible cytoprotective effects of GDF-15." (PMID 31772623, 2019).
lung cancer (33 papers, 2011 to 2026). A malignant neoplasm involving the lung. "GDF-15 exhibits strong potential as both a diagnostic and prognostic biomarker in lung cancer, distinguishing effectively between patients and healthy individuals." (PMID 40144214, 2025). "While there are some limitations to our analysis, it provides valuable insight into GDF-15’s role as a lung cancer diagnostic and prognostic marker." (PMID 40144214, 2025). "MDK and SPINT2 were selected due to the observed differences in overall survival while GDF15 levels have been associated with different stages of lung cancer in patients." (PMID 38260835, 2023). "Elevated plasma GDF15 levels are found in lung cancer patients with unintentional weight loss and is a predictor of poor prognosis." (PMID 37813923, 2023). "Other studies have found higher levels of circulating GDF-15 in patients with pulmonary fibrosis – a condition associated with high lung cancer risk." (PMID 34935094, 2022). "GDF-15 was further proposed as a diagnostic biomarker in, e.g., colorectal, ovarian, and early-stage lung cancer." (PMID 32508832, 2020). "However, overall survival data indicated that a high concentration of GDF-15 in MPE was associated with poorer outcomes in lung cancer patients (sFigure 3B and 3C)." (PMID 40959273, 2025). "Also, another prospective study also found that elevated GDF-15 levels in the elderly population were related to an increased lung cancer risk." (PMID 40144214, 2025). "Furthermore, elevated serum GDF-15 levels are associated with a poorer prognosis in lung cancer patients, underscoring their potential as a significant risk factor in clinical outcomes." (PMID 40144214, 2025). "Additionally, we investigated the association between three-year overall survival and GDF-15 levels in lung cancer patients." (PMID 40144214, 2025). "Each of these associations with lung cancer risk were strongly attenuated, however, when models were additionally adjusted for smoking status and educational level (in addition to alcohol consumption for GDF-15) and further covariates in model." (PMID 34935094, 2022). "Similarly, in a cross-sectional study of patients with lung cancer, GDF15 was associated with historical self-reported weight loss." (PMID 32310257, 2020). "Further studies with larger, more diverse populations are necessary to validate our findings and elucidate GDF-15’s role in lung cancer pathogenesis." (PMID 40144214, 2025). "We assessed and compared plasma GDF-15 levels between lung cancer patients and healthy controls by meta-analysis." (PMID 40144214, 2025). "The meta-analysis revealed a pooled sensitivity of 0.80 (95% CI: 0.71-0.87) and a specificity of 0.92 (95% CI: 0.85-0.96) for GDF-15 in distinguishing lung cancer patients from healthy individuals." (PMID 40144214, 2025). "In this study, we systemically analyzed all available literature regarding GDF15 as a biomarker for the diagnosis and prognosis of lung cancer." (PMID 40144214, 2025). "In conclusion, our analysis indicates that serum GDF-15 levels are significantly elevated in lung cancer patients compared to healthy individuals, serving as a useful biomarker for lung cancer diagnosis." (PMID 40144214, 2025). "GDF15 is a cytokine that has been found to be upregulated in a variety of tumor types, including breast, colorectal, and lung cancer." (PMID 38230211, 2024). "GDF15 therefore has been suggested as an auxiliary biomarker for the diagnosis and prognosis of various cancers, including lung cancer, for which a good correlation with clinical stage has been demonstrated." (PMID 36642986, 2023). "It is considered that GDF15 has a predictive role for PD-1/PD-L1 inhibitor treatment in patients with lung cancer." (PMID 36472770, 2023).
lung cancer (continued). "Several studies referred that GDF-15 promotes cancer proliferation and metastasis in colorectal, cervical, pancreatic and lung cancers." (PMID 35963873, 2022). "The GDF-15 levels of patients with mediastinal lymphoma or lung cancer who received thoracic radiotherapy were significantly higher after radiotherapy than before radiotherapy (1171ng/L increased to 1887ng/L)." (PMID 34859069, 2021). "Patients with gastrointestinal cancer were found more anorexic (based on the FAACT score) and showed higher GDF-15 serum levels than patients with lung cancer." (PMID 33396237, 2020). "Patients with gastrointestinal cancer resulted in being more anorexic and with higher GDF-15 levels than lung cancer patients." (PMID 33396237, 2020). "In chemically induced cancer models, transgenic overexpression of MIC-1/GDF15 leads to resistance to urethane induced lung cancer and azoxymethane induced colon cancer." (PMID 25695521, 2015). "GDF15 levels were notably higher in lung cancer patients than in healthy controls." (PMID 40144214, 2025). "In our study, we focused on the role of GDF15 in lung cancer." (PMID 40144214, 2025). "In Europeans, associations were consistent with East Asians for GDF15, GFRAL, and lung cancer." (PMID 40527012, 2025). "Hence, the plasma GDF-15 levels showed statistical significance between lung cancer patients and healthy controls in the meta-analysis." (PMID 40144214, 2025). "Additionally, the role of growth differentiation factor 15 (GDF15) has emerged as a biomarker associated with poor prognosis and drug resistance in various malignancies, including lung cancer with bone metastases." (PMID 40342734, 2025). "In addition, the level of GDF15 was slightly decreased in female lung cancer mice but was slightly increased after the ovary was removed." (PMID 35589688, 2022). "GDF15 is known to induce apoptosis in colorectal, prostate, and lung cancer cells." (PMID 29724997, 2018). "Therefore, GDF15 likely mediates the biological consequences of CDP138 knockdown in lung cancer cells." (PMID 28880265, 2017). "Importantly, GDF15 is identified as a critical downstream mediator of CDP138, indicating that the CDP138/GDF15/TGF-β pathway is a potential therapeutic target in lung cancer." (PMID 28880265, 2017). "To further confirm our working hypothesis, we examined the effect of CDP138 knockdown on GDF15-depleted lung cancer cells." (PMID 28880265, 2017). "Furthermore, we show that CDP138 knockdown attenuates the TGF-β/Smad signaling pathway via GDF15, ultimately impairing radioresistance and metastasis in lung cancer." (PMID 28880265, 2017). "GDF15 knockdown significantly suppressed proliferation and migration in lung cancer cells." (PMID 28880265, 2017). "However, CDP138 knockdown had minimal effect on the migration and radioresistance of GDF15-depleted lung cancer cells." (PMID 28880265, 2017). "GDF15 was the most downregulated gene in response to CDP138 depletion in lung cancer cells." (PMID 28880265, 2017).
lung cancer (continued). "Additionally, longitudinal studies tracking GDF-15 levels over time in lung cancer patients could deepen our understanding of its prognostic significance." (PMID 40144214, 2025). "Additionally, evaluation for the value of GDF15 in lung cancer chemotherapeutic response showed that GDF15 levels were significantly decreased in all patients after two cycles of treatment, regardless of the type of response to treatment; the effect was greater in the PR group." (PMID 36472770, 2023). "In addition, plasma GDF15 levels of enrolled patients did not correlate with age in this study, meaning that the changes caused by lung cancer are larger than the changes caused by general aging." (PMID 36472770, 2023). "It is thought that GDF15 affects the fraction of PD-1+ CD8+ T cells and PD-1+ Treg cells in patients with lung cancer, and this is related to the response to immunotherapy." (PMID 36472770, 2023). "More importantly, we demonstrate for the first time that growth differentiation factor 15 (GDF15) acts as a downstream mediator of CDP138-induced TGF-β/Smad signaling activation and mediates the biological effects of CDP138 in lung cancer cells." (PMID 28880265, 2017). "In conclusion, we elucidated the functions of CDP138 in lung cancer and demonstrated that CDP138 affects biological processes mainly via the GDF15-mediated TGF-β/Smad signaling pathway." (PMID 28880265, 2017). "The NSAID-activated gene (NAG-1, GDF-15, and MIC-1) is induced by several apoptosis-inducing agents in colon, prostate, and lung cancer cells." (PMID 23805285, 2013). "The lack of TK1 hinders the progression of lung cancer by decreasing GDF15 expression and metastatic capabilities." (PMID 39803822, 2025). "In lung cancer cells, GDF-15 was described to inhibit rather than activate the p38-MAPK and the PI3K-Akt-PKB and ERK1/2 pathways, resulting in enhanced apoptosis." (PMID 32508832, 2020). "This may not be a shared mechanism across cancer types, however, as GDF15 inhibited proliferation of lung adenocarcinoma cells, and low levels of GDF15 predicted poor prognosis in patients with non‐small cell lung cancer." (PMID 36642986, 2023). "Together, our findings demonstrate that CDP138 positively modulates the TGF-β/Smad signaling pathway via GDF15 to promote radioresistance and metastasis, suggesting CDP138 as a potential oncogenic biomarker and a promising therapeutic target in the treatment of lung cancer." (PMID 28880265, 2017). "However, GDF15 was identified as a protective factor for LUAD patients according to the univariate Cox analysis, and how GDF15 functions by ferroptosis process in lung cancer has not been reported." (PMID 34307361, 2021).
Mitochondrial myopathy (33 papers, 2016 to 2026). "In summary, our results demonstrated that GDF15 neutralization ameliorated body weight loss, attenuated muscle atrophy and improved muscle function and physical performance in a rodent model of mitochondrial myopathy (POLG)." (PMID 39976232, 2025). "Serum levels of growth differentiation factor (GDF-15), a sensitive diagnostic biomarker for mitochondrial myopathy, were reduced in these subjects." (PMID 33383961, 2020). "Three of these studies utilized non‐mitochondrial myopathy, such as Duchene Muscular Dystrophy or Spinal Muscular Atrophy, patients as control groups and found similar to lowered GDF15 levels compared to healthy controls." (PMID 40019842, 2025). "GDF-15 is a known mitochondrial disease biomarker that is particularly elevated in mitochondrial myopathies." (PMID 40760494, 2025). "In certain conditions, including cardiac stress, polycystic ovarian syndrome (PCOS), Kawasaki Disease (KD) and certain mitochondrial myopathies GDF15 can normalize with disease treatment or resolution." (PMID 40019842, 2025). "Published studies have indicated that GDF15 values greater than 1,200 pg/mL are useful for distinguishing mitochondrial myopathy from other types of metabolic myopathies and muscular dystrophies." (PMID 40271067, 2025). "These additional experiments and data will provide more mechanistic insights into the therapeutic mechanisms of GDF15 neutralization for mitochondrial myopathy and are warranted for future investigations." (PMID 39976232, 2025). "GDF15 is currently explored as a biomarker in many disorders including cardiovascular disease, cancer and mitochondrial myopathy." (PMID 37891738, 2023). "GDF-15 is a useful serum biomarker that helps distinguish between patients with chronic fatigue syndrome and those with mitochondrial myopathies exhibiting near-normal neurological examination (AUC > 0.9)." (PMID 36983435, 2023). "GDF-15 blood levels appear to be especially useful to diagnose early onset mitochondrial myopathy, and to identify mtDNA deletions and translation defects." (PMID 36361969, 2022). "Five studies that compared the performance of GDF-15 and FGF-21 as diagnostic biomarkers for mitochondrial myopathy all showed higher sensitivity of the former, three also allocated higher specificity to GDF-15." (PMID 36361969, 2022). "In humans, circulating levels of GDF-15 are elevated in patients with muscle atrophy and in patients with mitochondrial myopathy." (PMID 35735800, 2022). "Muscle manifestations are frequent in many human disorders, and GDF-15 serum levels reflect clinical characteristics and disease severity as seen in mitochondrial myopathies, but also in rheumatoid arthritis patients." (PMID 36361969, 2022). "In particular, patients with confirmed mitochondrial myopathy showed on average the highest GDF-15 levels, and contrary to FGF-21, GDF-15 concentration was ca. 3 times higher in patients presenting with MELAS." (PMID 34203775, 2021). "Patients of all ages, including children, with mitochondrial myopathy have higher levels of circulating GDF15 typically between 2–10 ng/mL compared to matched control groups, which exhibit levels of about 0.5 ng/mL." (PMID 34831213, 2021). "The authors went on to demonstrate markedly elevated circulating GDF15 in children with mitochondrial myopathies (mean: 3562 pg/ml, large range with max value almost 90 000 pg/ml), but not in nonmitochondrial myopathies such as the muscular dystrophies." (PMID 32310257, 2020). "In a separate study, rapamycin treatment completely inhibited Gdf15 induction in a mouse model of mitochondrial myopathy, implicating mTORC1 signaling." (PMID 32310257, 2020). "Serum GDF-15 levels have recently been revealed as a sensitive and specific biomarker for the diagnosis of mitochondrial myopathies." (PMID 31060578, 2019). "For instance, circulating GDF15 levels are increased in patients with cancer, cardiovascular disease, muscle atrophy and mitochondrial myopathy." (PMID 30687235, 2018).